IL6 (interleukin 6)
Diseases named in the same sentence as IL6 in open-access papers (continued):
Sharing a sentence is not in itself a finding about the gene and the disease.
hepatocellular carcinoma (continued). "In summary, we demonstrated that hepatoma cell-derived exosomes induced KCs to differentiate into TAMs, thereby secreting IL6." (PMID 39744421, 2025). "A preclinical investigation proved that inhibiting IL-6 effectively reestablished the mice’s resistance to anti-PD-L1 treatment in hepatocellular cancer models." (PMID 40433391, 2025). "To this end, we generated a rabbit polyclonal anti-p-ACAP4Y843 antibody and tested the endogenous protein level of ACAP4 phosphorylated at Tyr843 in the absence or presence of IL6 stimulation in hepatoma cells." (PMID 39744421, 2025). "It contributes to liver health by slowing hepatocellular carcinoma (HCC) progression, improves metabolic health by enhancing insulin sensitivity and reducing diabetes risk, and lowers inflammation by reducing oxidative stress and cytokines like IL-6 and TNF-α." (PMID 40718363, 2025). "A recent study showed that Shp overexpression suppresses the occurrence of hepatocellular carcinoma in aged Nh1h4-KO mice, partly by reducing serum bile acid and IL-6 levels." (PMID 40499905, 2025). "Research has shown that IL-6, activin-A, and granulocyte colony-stimulating factor (G-CSF) in the tumor microenvironment promote the dedifferentiation of hepatocellular carcinoma cells as well as thyroid cancer cells." (PMID 40535127, 2025). "After logistic multifactorial analysis, intact envelope, tumor > 5 cm, AFP, CAR, CD147, and IL-6 were identified as independent influencing factors for invasive metastasis of primary hepatocellular carcinoma (all p < 0.05)." (PMID 40919145, 2025). "Hepatocellular carcinoma patients derived CAFs (HCC-CAFs) release IL-6, stimulating PD-L1 expression on neutrophils via the STAT3 pathway." (PMID 39287890, 2025). "Earlier studies have reported the role of sex hormones, transcription factors FoxA1/A2, and cytokine Il6 signaling in regulating the sex difference in hepatocellular carcinoma (HCC), but the role of metabolic pathways remains poorly understood." (PMID 41460563, 2025). "LJF extract has been found to mitigate TNF-α or IL-6-induced inflammatory responses in hepatocellular carcinoma and macrophage cell lines by inhibiting NF-κB/IL-6/STAT3 signaling, thereby reversing immune suppression." (PMID 39314630, 2024). "Norcantharidin, an effective IL-6 inhibitor, enhances the antitumor activity of sorafenib in a rat model of hepatocellular carcinoma through the IL-6–STAT3 pathway." (PMID 38379418, 2024). "UA significantly decreased P-STAT3, which produces interleukin-6 (IL-6) in hepatocellular cancer cells." (PMID 38397437, 2024). "IL-6 promotes PD-L1 expression in human hepatocellular carcinoma (HCC) through the JAK/STAT3 signaling pathway, thereby reducing the expression of protein tyrosine phosphatase receptor and further promoting tumor immune escape." (PMID 39286258, 2024). "We investigated the effects of macrophage infiltration and IL‐6 expression on the development of human hepatocellular carcinoma (HCC)." (PMID 37974543, 2024). "Because of anti-PD-L1 resistance in hepatocellular carcinoma, CAFs expressing high levels of IL-6 support the disruption of tumor-infiltrating T-cell function, resulting in the generation of immunosuppressive cells in the TME." (PMID 39075612, 2024). "Significantly high levels of cytokines, interleukin-5 (IL-5) and interleukin-6 (IL-6), were reported in the patients diagnosed with hepatocellular carcinoma compared to the healthy patients." (PMID 39408564, 2024). "For example, the IL-6/STAT3 pathway has been identified as a promoter of angiogenesis in hepatocellular carcinoma by enhancing endothelial cell migration and angiogenesis." (PMID 39695099, 2024). "Thyroid hormone T3 inhibits IL-6 signaling in macrophages and hepatocellular carcinoma cells, suppresses STAT3 activation, and prevents the deleterious effects of excess hormone signaling during infection." (PMID 38022688, 2023).
hepatocellular carcinoma (continued). "In conclusion, we demonstrated that PD1 + TIM3+/T, TIGIT + T/T, and IL-6 levels after immunotherapy can serve as predictors of efficacy in patients with hepatocellular carcinoma." (PMID 38110467, 2023). "We aimed to investigate the correlation between lymphocyte subpopulations expressing inhibitor receptors, IL-6 levels, and the efficacy of immunotherapy in patients with hepatocellular carcinoma." (PMID 38110467, 2023). "ISX was induced by the pro-inflammatory cytokine interleukin-6 and was highly expressed as a proto-oncoprotein in hepatoma cell and HCC samples." (PMID 37444447, 2023). "Similar observations were found in adipocytes co-cultured with exosomes derived from hepatocellular carcinoma, where the induction of pro-inflammatory cytokines IL-6, IL-8, IL-1β and CCL2 promoted tumor growth and angiogenesis." (PMID 37833751, 2023). "Patient-derived hepatocellular carcinoma (HCC)-CAFs secrete IL-6 which induces PD-L1 expression on neutrophils via the STAT3 pathway." (PMID 37480115, 2023). "For example, human hepatocellular carcinoma-derived CAFs can secrete IL-6, which upregulates the activation of the STAT3 signaling pathway in DCs and creates a regulatory DC (rDC) phenotype that can’t prime and activate T lymphocytes." (PMID 37007004, 2023). "TAM-derived IL-6 induces tumorigenic and invasive effects and promotes breast, colorectal, and hepatocellular cancer or gastric tumor chemoresistance through the STAT3 signaling pathway." (PMID 36838713, 2023). "Some mechanistic studies using human hepatoma HepG2 cells found that IL-1 can inhibit cholesterol synthesis and decrease cholesterol and Apo-B secretion, and IL-6 can increase cholesterol synthesis but decrease even more cholesterol secretion." (PMID 37692785, 2023). "It was found that miR-515-5p inhibits hepatocellular carcinoma progression by inhibiting IL6/JAK/STAT3." (PMID 38025711, 2023). "Of note, it has been recently shown the involvement of a Cu-dependent amine oxidase in the activation of the IL6/JAK/STAT3 axis required for the progression of hepatocellular carcinoma." (PMID 36454513, 2023). "In conclusion, interleukin-6 assumes a pivotal role in hepatocellular carcinoma, the predominant liver cancer type." (PMID 37892997, 2023). "CAFs-produced IL-6 induces a tolerogenic phenotype in hepatocellular carcinoma DCs, increases tumor infiltration of immunosuppressive regulatory T cells (Tregs) (CD4CD25Foxp3), and decreases IFN-γ production by CD8 T cells." (PMID 37007004, 2023). "It has also been found that increased IL-6 level is negatively correlated with the overall survival and progression-free survival of hepatocellular carcinoma patients." (PMID 38110467, 2023). "RIP140 overexpression inhibits NF‐κB/IL‐6 axis activation, thereby suppressing M2 polarization to hinder hepatocellular carcinoma cell growth and proliferation." (PMID 38098217, 2023). "A previous study demonstrated that IL-6 generated by TAMs induces upregulation of CD47 on hepatoma cells via the STAT3 signaling pathway, subsequently influencing TAM-mediated phagocytosis, promoting tumor progression in HCC, and leading to poor prognosis." (PMID 37305578, 2023). "For example, the NF-κB target gene IL-6 has been shown to induce APOBEC3B expression in hepatocellular carcinoma via JAK/STAT signaling." (PMID 36978147, 2023). "Maximum CRP expression is seen in cells treated with both IL-6 and IL-1 in human hepatoma Hep3B cells." (PMID 37860004, 2023). "lncRNA DILC can inhibit multiple signaling pathways such as NF-κB and STAT3 to affect the proliferation of hepatocellular carcinoma stem cells by suppressing the transcription of IL-6." (PMID 37480035, 2023). "Previously, it was documented that IL-6 is capable of suppressing replication of HBV together with inhibiting the accumulation of HBV-covalently closed circular DNA (ccc DNA) in human hepatoma cells." (PMID 35119591, 2023).
hepatocellular carcinoma (continued). "In another study of hepatocellular carcinoma, IL-37 converted M2 TAMs into M1 cells by inhibiting the IL-6/STAT3 signaling pathway." (PMID 38033495, 2023). "Another investigation showed that the expanded TAM-inferred IL-6 has an intensifying impact on the inflammation responses, advancing the event and improvement of hepatocellular carcinoma as liver cancer employing STAT3 signaling." (PMID 37211559, 2023). "LMT-28 also affected the IL-6 expression in a variety of cells, such as hepatoma cells, erythroleukemic cells, and fibroblast-like synoviocytes." (PMID 36643585, 2023). "Preliminary studies have suggested that the combined targeting of IL-6 and PD-L1 achieved synergistic effects on inhibiting pancreatic ductal and hepatocellular carcinoma growth in mouse models." (PMID 35265072, 2022). "In particular instances, sex-specific expression of IL-6 by macrophages accounts for the 3-5-fold increased prevalence of hepatocellular carcinoma in men compared to women." (PMID 35406728, 2022). "The relationship between IL-6 and exosomal miRNAs related to hepatocellular carcinoma (HCC) metastasis remains to be elucidated." (PMID 35432524, 2022). "High levels of interleukin 6 (IL)-6 generated by TAMs stimulate the proliferation of hepatocellular carcinoma CSCs in vitro." (PMID 36613838, 2022). "At the protein level, RasGRP1 overexpression significantly inhibits the tumour-promoting effect of IL-6 in hepatocellular carcinoma progenitor cell-like spheroids." (PMID 36385095, 2022). "Specifically, the IL-6/STAT3 signaling pathway was also confirmed to be inhibited in M1-type macrophages but activated in M2-type macrophages in hepatocellular carcinoma (HCC)." (PMID 35432300, 2022). "In the same study, they show that IL-17F inhibits microvessel formation and that it downregulates VEGF, IL-6, and IL-8 expression in hepatocellular carcinoma." (PMID 35626056, 2022). "IL-6 directly acts on hepatocellular carcinoma (HCC) cells to induce the expression of signal transducer and activator of transcription 3 (STAT3) target genes, which encode proteins (including IL-6) and drive tumor proliferation and/or survival." (PMID 35223512, 2022). "It was observed in hepatocellular carcinoma that IL-17-driven AKT signaling activation resulted in IL-6 production, which in turn activated JAK2–STAT3 signaling and subsequently upregulated its downstream targets, IL-8, MMP2, and VEGF." (PMID 35884700, 2022). "IL-37 overexpression by TAMs derived from patients with human hepatocellular carcinoma (HCC) inhibits M2 polarization via regulation of the IL-6/STAT3 pathway, to suppress tumor growth in vivo." (PMID 36551790, 2022). "CRP synthesis, on the other hand, was shown to be mainly regulated by IL-6 in the hepatoma cell lines." (PMID 35883605, 2022). "When transfected into hepatoma cells, HBx promotes the production of IL-6 that participates in the activation of STAT3." (PMID 36298831, 2022). "Increasing glucose concentrations in cell culture medium has also been shown to increase IL-6 production and secretion across various cell types, including hepatocellular carcinoma and cholangiocarcinoma." (PMID 35457130, 2022). "OA, on the other hand, has been reported to significantly inhibit IL-6 levels in insulin-resistant human hepatoma (HepG2) cells and inhibit the secretion of IL-6 from differentiating 3T3-L1 adipocytes." (PMID 36558948, 2022). "We focused on the precise effect of extract from leaves ofAzadirachta indica Juss, on inhibiting the IL-6/STAT3 signaling cascade on hepatocellular carcinoma byin vitro andin vivo study." (PMID 37829248, 2022). "have evaluated CAF-regulated neutrophil function and the activation of hepatocellular carcinoma (HCC) via the IL-6/STAT3/PD-L1 signaling cascade." (PMID 35464435, 2022). "Macrophages produce growth factors for cancer cells such as IL‐6, which is critical for hepatocellular carcinoma, via Stat3 activation." (PMID 35132816, 2022).
hepatocellular carcinoma (continued). "Exosomal miR-1247-3p derived from highly metastatic hepatocellular carcinoma cells activated CAFs, which in turn promoted cancer progression by secreting IL-6 and IL-8." (PMID 35443745, 2022). "In palmitic acid (PA)-treated human hepatocellular carcinoma HepG2 cells, the downregulation of miR-375 expression significantly reduced IL-6, TNF-α, and leptin, and increased adiponectin levels." (PMID 36613525, 2022). "In murine models of hepatocellular carcinoma, TLR2-deficient mice showed a decrease in the expression of IFN-γ, TNF-α, (IL)-1α/β, IL-6, and Cxcl-2, which attenuate p21- and p16/pRb-dependent senescence, leading to the increased proliferation of tumor cells." (PMID 35309296, 2022). "Studies have shown that IL-6 played a clear role in liver deterioration and tumor progression, directly affecting the survival of hepatocellular carcinoma patients." (PMID 36324154, 2022). "Hepatocellular carcinoma– derived CAFs were demonstrated to recruit neutrophils by secreting SDF1a and facilitating neutrophils’ activation via IL-6-JAK-STAT3 signaling." (PMID 36189283, 2022). "In rat hepatoma cells, loss of methylation events in the IL-6/STAT3 promoter was related to higher IL-6 levels and higher proliferation rates." (PMID 34944023, 2021). "In hepatocellular carcinoma, miR-515-5p inhibits the invasion and migration of cancer cells by suppressing the IL6/JAK/STAT3 pathway." (PMID 33539322, 2021). "In hepatocellular cancer, the interaction between MDSCs and IL-6 promoted the generation of a chemoresistant phenotype." (PMID 33981768, 2021). "First, the effect of cryptolepine on the IL-6/STAT3 pathway in human hepatoma cells (HepG2 cells) was screened using the Cignal Finder Multi-Pathway Reporter Array." (PMID 34078370, 2021). "Combined targeting of IL-6 and PD-L1 resulted in enhanced inhibitory effects on tumor progression in mouse models of both pancreatic cancer and hepatocellular carcinoma." (PMID 34001144, 2021). "The increased expression of LIN28 leads to the secretion of IL-6, which makes HcPC differentiate into hepatocellular carcinoma cells." (PMID 35096588, 2021). "Continuous stimulation of the inflammation-related IL-6 pathway contributes greatly to the activation of hepatocellular carcinoma, which eventually leads to the proliferation and invasion of liver tumors." (PMID 34194957, 2021). "Ectopic expression of IRE1α or XBP1s robustly enhances the expression and secretion of IL-6 in hepatocellular carcinoma and melanoma cells." (PMID 34295814, 2021). "The activation of STAT3 by IL-6 results in macrophage polarization into M1 macrophages, which are involved in the development of hepatocellular carcinoma (HCC)." (PMID 34576053, 2021). "In this study, we analyze the influence of different compounds that modulate the actin cytoskeleton on NF-κB activation, IL-6 signaling and the proteolytic generation of the soluble IL-6 receptor (sIL-6R) in human hepatoma cells." (PMID 34281231, 2021). "A most recent study has shown that increased serum IL-6 downregulated PTPRO expression in human hepatocellular carcinoma (HCC) monocytes and macrophages." (PMID 34650968, 2021). "It was also reported that IL-17A activates the IL-6/STAT3 signal pathway followed by cell proliferation in hepatocellular carcinoma." (PMID 34445513, 2021). "Based on the C5AR1, HBc facilitates the activation of intracellular signal pathways (such as c-Jun N-terminal kinase (JNK) and ERK pathways) as well as the expression and secretion of interleukin (IL)-6 in hepatoma cells." (PMID 34948447, 2021). "Previous studies described that human hepatoma cells and hepatic cells secrete IL-6 after activating NF-κB pathway and a MyD88-dependent signaling pathway, whose activation is regulated by protein phosphatase type 2 C alpha in the presence of HBx protein." (PMID 34948447, 2021).
hepatocellular carcinoma (continued). "Previous studies reported that Icaritin inhibits the growth of liver cancer cells through promoting the apoptosis of hepatoma cells by activating the caspase pathway and inhibiting the IL-6/Jak2/Stat3 signaling pathway." (PMID 33794968, 2021). "Given that IL-6 plays a key role in regulating inflammatory hepcidin expression by activating STAT3, we examined the roles of DP in the expression of JAK2, p-JAK2, STAT3, and p-STAT3 in HepG2 hepatoma cells treated with IL-6." (PMID 33488942, 2021). "Nuclear factor-kappa B in the NF-kB/IL-6/STAT3 pathway plays an important oncogenic role in cancers that arise from chronic inflammation such as hepatocellular carcinoma." (PMID 35154607, 2021). "In hepatocellular carcinoma patients treated with RT, levels of IL-6 and IL-10 were seen to be valuable predictors of infield- and outfield-intrahepatic treatment failure." (PMID 34768644, 2021). "Recent studies demonstrate that there is a possible crosstalk between the BMP/SMAD and the IL-6 mediated JAK/STAT3 pathway at inflammation in hepatoma cell lines and primary mouse hepatocytes." (PMID 33835366, 2021). "We show herein that pharmacological iron chelation slightly impaired hepcidin induction by BMP6 and/or IL-6 primarily in human Huh7 hepatoma cells." (PMID 34161397, 2021). "For example, IL-17 activates the IL-6/STAT3 signal pathway in the proliferation of hepatitis B virus-related hepatocellular carcinoma." (PMID 33859718, 2021). "In mouse models of hepatocellular carcinoma and melanoma, reductions in tumor burden are related to diminished IL-6 levels and impaired MDSC function." (PMID 33854974, 2021). "In the study by Shuai Wang, the NEAT1 paraspeckle promoted the progression of human hepatocellular carcinoma by increasing IL-6/STAT3 signalling." (PMID 33546665, 2021). "The induction of HO-1 by IL-6 has been investigated by several cell types, including human hepatoma cells." (PMID 32204510, 2020). "miR-9 is frequently down-regulated in primary hepatocellular carcinoma and its restoration retards cell proliferation and migration by targeting IL-6, AP3B1, TC10, OC2, IGF2BP1, MYO1D, and ANXA241." (PMID 32393810, 2020). "Different IL-6 pathways are involved in the physiology and pathophysiology of the liver and they are crucial for the development of hepatocellular carcinoma." (PMID 32204510, 2020). "In HBx induced hepatocellular carcinoma mice model, IL-6/STAT3, and Wnt/β-catenin signaling pathways are constitutively activated." (PMID 33234142, 2020). "In diethylnitrosamine (DEN)-induced hepatocellular carcinoma mouse models, male-specific production of IL6 was reported to induce hepatocellular carcinoma." (PMID 32546802, 2020). "In this study, we aim to elucidate the function of HO-1 on human hepatoma cells and to investigate molecular mechanisms whereby IL-6 modulates human HO-1 gene expression." (PMID 32204510, 2020). "IL-6 secreted by TAMs is highly correlated with the occurrence and development of hepatic carcinoma via activating STAT3 pathway." (PMID 31903134, 2020). "ISX, a pair‐family homeobox TF, is a pro‐inflammatory cytokine (IL‐6)‐induced homeobox gene that is highly expressed in hepatoma cells from patients with hepatocellular carcinoma (HCC)." (PMID 31908141, 2020). "In hepatocellular carcinoma cells (HepG2), evodiamine effectively hindered constitutive and IL-6-induced activation of STAT3 (Tyr705) phosphorylation." (PMID 32545187, 2020). "H22 hepatoma bearing mice treated with DCs and DCs stimulated by ESPs showed a decrease in IL-4, IL-6, or IL-10 compared with their levels in the PBS and ESP groups (p < 0.05)." (PMID 32692308, 2020). "In order to determine the anti-inflammatory characteristics of HO-1 in hepatoma cells, we evaluated the effect of HO-1 on IL-6 gene expression." (PMID 32204510, 2020).